APOE (apolipoprotein E)
Diseases named in the same sentence as APOE in open-access papers (continued):
Sharing a sentence is not in itself a finding about the gene and the disease.
neurodegenerative disease (continued). "ApoE has been found to be involved in neurotoxicity, mitochondrial dysfunction, and neurodegenerative diseases, particularly AD." (PMID 30935111, 2019). "In any case, the outstanding appearance of apoE in AD and other neurodegenerative diseases is attributed to the fact that lipid transport in cerebrospinal fluid (CSF) is mediated by HDL particles rich in apoE." (PMID 31071995, 2019). "Nevertheless, cell-type specific roles for APOE isoform expression, secretion, and lipidation in neurodegenerative disease remain poorly understood." (PMID 31623648, 2019). "Recently, RNAseq data suggested APOE in combination with TREM2 to induce the microglial phenotypic changes observed in neurodegenerative diseases." (PMID 30459560, 2018). "This novel study provides many answers regarding the relationship between TREM2 and ApoE in neurodegenerative diseases." (PMID 30572908, 2018). "A new study has shed light on the function of the TREM2/ApoE connection in neurodegenerative diseases including AD." (PMID 30572908, 2018). "Here, we review data supporting the involvement of apoE structural domains and isoforms in normal and altered lipid metabolism, cardiovascular and neurodegenerative diseases, as well as stress-related pathological states." (PMID 28660014, 2017). "Knowing that the TREM2/ApoE interaction is presumably relevant to AD pathogenesis and perhaps also to other neurodegenerative diseases, we found it essential to determine the extent to which human ApoE stimulated murine TREM2 signaling." (PMID 28320424, 2017). "When we verified association for loci specific to other neurodegenerative diseases, we identified the TOMM40/APOE locus reaching p value of 2.1 × 10−5 (rs2075650; OR = 1.65) in our FTD cohort." (PMID 26154020, 2015). "APOE4 targeted gene replacement and APOE knockout mice have been found with increased pro-inflammatory states, an effect that is potentially undesirable for neurodegenerative diseases, but beneficial during exposure to gut-infectious pathogens early in life." (PMID 24586873, 2014). "The identification of molecules that modulate innate immune activation in AD and other neurodegenerative disease is needed to identify potential therapeutic targets; a strong candidate molecule is apolipoprotein E (apoE)." (PMID 22883744, 2012). "We identify a conserved, systemic pro-inflammatory immune proteomic signature associated with APOE ε4 across plasma, CSF and brain, irrespective of neurodegenerative disease or pathology." (PMID 40665049, 2025). "Moreover, ApoE ε4 can contribute to the development and progression of neurodegenerative diseases by affecting the metabolism and clearance of amyloid-β, cellular membrane stability, and neuronal function." (PMID 40638992, 2025). "ApoE is a key modulator of protein aggregation and internalization in neurodegenerative diseases." (PMID 40362276, 2025). "These insights enhance our understanding of APOE’s conformational dynamics and may inform future studies on its role in neurodegenerative disease mechanisms." (PMID 41465183, 2025). "The apolipoprotein E (APOE) gene is known to impact the onset of neurodegenerative diseases." (PMID 41439935, 2025). "Nevertheless, it is important to continue the efforts in dissecting the mechanisms that are affected by APOE variants in the presence and/or absence of aSyn and in other neurodegenerative diseases." (PMID 39996490, 2025). "Using mutual information, we identified 58 plasma proteins in nonimpaired controls that were associated with APOE genotype and led to clustering based on the number of APOE ε4 alleles rather than by neurodegenerative disease." (PMID 40665049, 2025). "By enabling cross-disease comparisons, such efforts may help delineate modifiers that influence why some APOE ε4 carriers develop AD while others remain healthy or develop different neurodegenerative diseases." (PMID 40665049, 2025).
neurodegenerative disease (continued). "While APOE in the brain is mainly produced by astrocytes, recent studies have shown that particularly APOE4 also plays a role in the dysregulation of microglial cells in neurodegenerative diseases and might contribute to the severity of these diseases." (PMID 41253293, 2025). "Functional enrichment analyses revealed that three of the main biological processes (viral processes, negative regulation of apoptosis, and protein folding) identified in the CSF and plasma were also significantly enriched in the dlPFC of APOE ε4 carriers across all neurodegenerative diseases." (PMID 40665049, 2025). "Notably, this suggests that although the biological changes associated with APOE ε4 carriage are essential for neurodegeneration, broadly, interactions with underlying biological vulnerability and the environment may be key for driving the pathogenesis of the specific neurodegenerative disease." (PMID 40665049, 2025). "Across all neurodegenerative disease groups, we identified 248 APOE ε4 proteins." (PMID 40665049, 2025). "Incidentally, the APOE ε2 allele that is protective in AD confers risk in AMD, whereas APOE ε4 is protective in AMD, highlighting the complex roles of these gene pathways in different neurodegenerative diseases." (PMID 38247923, 2024). "APOE is a potential therapeutic target in neurodegenerative disease." (PMID 38792885, 2024). "Hence, clarifying the role of ApoE in tau pathology is central to understanding the development and progression of several neurodegenerative diseases." (PMID 39524360, 2024). "Furthermore, apolipoprotein E (APOE) and TREM2, known to be neurodegenerative disease risk genes, are enriched in microglia purified by the adult human brain." (PMID 39456734, 2024). "We saw that these genes of interest could be linked to known familial neurodegenerative disease genes (APP and HTT), and AD risk genes (APOE and PLCG2) from prior experimental studies using the Ingenuity database." (PMID 39231932, 2024). "APOE genotype may shape regionally specific patterns of cellular changes occurring with aging and neurodegenerative disease, with effects of normal aging predominating in the absence of pathogenic drivers." (PMID 38212861, 2024). "TREM2 activation by APOE induces significant changes in microglia gene expression and in models of neurodegenerative diseases, such as APP-PS1 mice (a model for AD); the activation of this signaling pathway is associated with increased amyloid plaque pathology." (PMID 39456734, 2024). "On the other hand, cerebrovascular lesions and other neurodegenerative diseases did not mediate the association between APOE-ε4 and cognition." (PMID 38115150, 2023). "Furthermore, myelin is highly enriched in cholesterol, which is emerging with apolipoprotein E as an important factor in white matter impairment in aging and neurodegenerative diseases." (PMID 37578550, 2023). "sEVs do not only act on recipient cells through miRNAs and lncRNAs but also play physiological functions by delivering proteins, such as polymorphic apolipoprotein E (ApoE), which plays a key role in cardiovascular and neurodegenerative diseases and inhibits tumor growth." (PMID 35832790, 2022). "We considered this possibility because PAS granules and CA are known to be closely associated with and likely generated within astrocytes, cells that are increasingly reactive in neurodegenerative diseases, naturally aged mice, and human APOE E4 knock-in (KI) models." (PMID 35941704, 2022). "Some points that could not be discussed further in depth in this review are the implications of peripheral versus CNS apoE and the impact of the gut-brain axis in the development of neurodegenerative diseases." (PMID 36153580, 2022). "Hence, we also aim to comment on the influence of the APOE genotype in other neurodegenerative diseases." (PMID 36153580, 2022). "However, the role of ApoE in lipoprotein metabolism of various neurodegenerative diseases needs further discussion." (PMID 35840315, 2022).
neurodegenerative disease (continued). "Our findings support age‐, sex‐, and APOE‐related microglial transcriptome changes involving lipid and carbohydrate metabolic pathways and implicate microglial immunometabolism perturbations relevant to neurodegenerative diseases." (PMID 35388616, 2022). "The structural and functional differences between apoE isoforms have been shown to confer differential susceptibility to neurodegenerative diseases such as AD and LBD, with APOE4 increasing the risk while APOE2 is protective compared with the more common APOE3 allele." (PMID 36419137, 2022). "Despite this link with DLB and FTD, APOE has not clearly been associated with other neurodegenerative diseases, implying that APOE is not a major contributor to disease risk for these disorders." (PMID 36337698, 2022). "Altogether, APOE might share common mechanisms of action among neurodegenerative diseases with an abnormal protein accumulation or an acute detrimental event." (PMID 36153580, 2022). "These consisted of markers of astrocytic and microglial activation (GFAP, vimentin, galectin-1, and clusterin) and indicators of neurodegenerative disease (ApoE and serpinA3N) that each demonstrated significant prion effects and PAM effects from the MS proteomic analysis." (PMID 36378750, 2022). "However, sex differences in the effect of the APOE genotype have already been reported in the context of neurodegenerative diseases, along with sex differences in hepatic fat oxidation or de novo lipogenesis." (PMID 36532543, 2022). "Further follow-up studies are needed to investigate the significant associations between APOE and LATE-NC, though even if null this association would still highlight the strong associations that exist between AD and other neurodegenerative diseases, which is interesting in itself." (PMID 34526147, 2021). "ApoE is a multifunctional protein involved in lipid metabolism and neurodegenerative diseases." (PMID 34563206, 2021). "The present study suggests that astrocytic ApoE may play a role in the progression of neurodegenerative disease resulting from impaired hippocampal newborn neurons." (PMID 34795427, 2021). "Treatment with statins is stratified by sex, APOE ε4 genotype, and degenerative diseases." (PMID 33969178, 2021). "Similarly, ApoE (ApoE4) isoforms have been related to neurodegenerative diseases, decreased recycling, and cholesterol redistribution in the central nervous system." (PMID 34829788, 2021). "Future studies will further explore the relationship between APOE ε4 and CSF Ng and related mechanisms, providing more evidence for the potential roles of Ng in clinical research, trials and practice of AD and other neurodegenerative diseases." (PMID 33986657, 2021). "While informative, current research focusing on APOE-ε4 allele-dependent gene expression has failed to integrate other heritable factors associated with neurodegenerative diseases." (PMID 33540525, 2021). "Consequently, ApoE is an extraordinarily significant gene for regulating Aβ abnormalities in neurodegenerative diseases." (PMID 31843449, 2020). "Apart from the membrane-associated proteins, exosomes isolated from cerebrospinal fluid (CSF) were also rich in proteins derived from the brain, such as microglial markers (CD11b and CD45), neuron-specific markers and apolipoprotein E (Apo-E), involved with neurodegenerative diseases." (PMID 30965555, 2019). "We overexpressed the three major human ApoE isoforms in N9 cells, which is resembling disease situation and where we likewise detected significant upregulation of ApoE expression in mouse models of neurodegenerative diseases and human AD." (PMID 31130847, 2019). "Moving forward, these mice should prove an invaluable asset for further studies on the physiological and pathophysiological roles of APOE, especially the role of apoE isoforms in specific cell types and different organs in the context of AD and other neurodegenerative diseases." (PMID 31623648, 2019).
neurodegenerative disease (continued). "APOE began to appear as one of the best examples of genetic “antagonistic pleiotropy” (AP), a concept applicable to human traits and diseases, and to human cognition, neurodegenerative diseases, and brain diseases in general." (PMID 30677746, 2019). "Collectively, these data have identified widespread evidence for apoE fragmentation in the human PD brain and documented for the first time the presence of apoE within Lewy bodies, the major pathological marker for this neurodegenerative disease." (PMID 30272057, 2018). "Our results indicate that APOE ε2 is not benign with respect to risk for neurodegenerative diseases, which should be taken into consideration in future clinical trial design and early prevention strategies for tau-related disorders." (PMID 30348994, 2018). "Speculating, failure of glymphatic CSF inflow into brain, as in sleep deprivation, may, in the long-term, contribute to apoE related disorders and eventually neurodegenerative diseases." (PMID 27931262, 2016). "Overall, our study reveals a conserved APOE ε4-associated pro-inflammatory immune signature persistent across the brain, CSF and plasma irrespective of neurodegenerative disease, highlighting a fundamental, disease-independent biological vulnerability to neurodegeneration." (PMID 40665049, 2025). "Twenty-seven of these associations are known disease loci reported in GWAS, including APOE, MME, CD2AP, CD33 and IL34 for AD, and CD40, CD58, EVI5, IL7R and STAT3 for MS, and 23 associations represent previously unreported genetic associations with neurodegenerative diseases." (PMID 40037332, 2025). "While this chronic immune activation may predispose APOE ε4 carriers to neurodegeneration, it is unlikely to be sufficient alone to drive the development of neurodegenerative disease." (PMID 40665049, 2025). "This work reframes APOE ε4 as a pleiotropic immune modulator rather than an AD-specific risk gene, providing a foundation for precision biomarker development and early intervention strategies across neurodegenerative diseases." (PMID 40665049, 2025). "APOE reportedly plays an important role in maintaining brain lipid homeostasis and regulating microglial responses and related lipid metabolism during nerve injury, which may contribute to the development of neurodegenerative diseases." (PMID 38892402, 2024). "Despite impressive research and therapeutic advances in both fields of preE and neurodegenerative diseases, further investigation of Pin1-cis P-tau and ApoE-related mechanistic underpinnings may unravel novel therapeutic options, and new transcriptional and proteomic markers." (PMID 39857613, 2024). "Thus, understanding how apoE isoforms regulate microlgial behaviors and their impacts on demyelination and myelin recovoy may shed lights on their roles in AD and other neurodegenerative diseases." (PMID 36419137, 2022). "Thus, reducing apoE-mediated myelin debris and LD accumulation may be beneficial in maintaining microglial homeostasis to mitigate neurodegenerative disease." (PMID 36419137, 2022). "Thus, the apoE-centric screening methods and drug candidates we report here may also prove valuable for addressing other human neurodegenerative diseases." (PMID 35768831, 2022). "ApoE was previously thought to be expressed mainly in astrocytes, however, a recent transcriptome analysis of human brain cells showed that ApoE transcripts are also expressed in microglia, which links cholesterol metabolism in microglia to neurodegenerative diseases." (PMID 35831869, 2022). "Overall, our findings indicate that apoE plays a critical role in modulating microglial responses and related lipid metabolism upon neuronal injury, which may contribute to the development of neurodegenerative diseases." (PMID 36419137, 2022).
neurodegenerative disease (continued). "In neurodegenerative diseases, a specific type of microglia was found, subsequently classified as disease-associated microglia (DAM) characterized by transcriptional changes driven by apolipoprotein E (APOE) and the triggering receptor expressed on myeloid cells 2 (TREM2)." (PMID 34054862, 2021). "In addition to AD, our results imply that ApoE may also play isoform-specific roles in other neurodegenerative diseases involving ROS-induced apoptosis." (PMID 34769014, 2021). "Whether these glial-specific ApoE-HDLs differentially impact neurodegenerative disease is unclear." (PMID 33924200, 2021). "Therefore, ApoE might be a critical factor in the dysregulation of microglia cells by inducing a specific transcriptional program in neurodegenerative diseases." (PMID 31130847, 2019). "This indicates that the 10 most connected neighbors of APOE (or other genes of interest in AD and other neurodegenerative diseases) could potentially be used as biomarkers, and that genome-wide association studies (GWAS) could provide good candidates to predict individuals’ delta MMSE." (PMID 27703197, 2016). "Thus, APOE gene has become a significant target for investigation in neurodegenerative diseases." (PMID 24175296, 2013). "In various mouse models of neurodegenerative diseases and human brain samples, researchers have discovered that TREM2 activation induced by apoptotic neurons triggers the APOE signaling pathway." (PMID 40722268, 2025). "Notably, APOE ε4-associated changes are independent of neurodegenerative disease, whether measured simply by diagnosis or by specific pathological changes in the brain." (PMID 40665049, 2025). "Among the affected genes were APOE (apolipoprotein E), SEMA3C (semaphorin 3C), and NTNG1 (netrin G1), which have established roles in energy regulation and neurodegenerative disease." (PMID 41009961, 2025). "Several ALS-increased DEGs had previously been recognized as markers for microglia phenotypes detected in other neurodegenerative diseases (e.g., GPNMB, APOE, LTA4H)." (PMID 40700130, 2025). "Apolipoprotein E (APOE) is a multifaceted protein with roles in lipid metabolism, neurobiology, and neurodegenerative diseases." (PMID 38637538, 2024). "Our work highlights the potential of ASOs as a research tool to study the functions of APOE and TREM2 in neuroinflammation and as a potential therapeutic modality to interfere with the role of microglia and neuroinflammation in neurodegenerative diseases." (PMID 38654375, 2024). "Apolipoprotein E (APOE) is a multifunctional protein pivotal in lipid metabolism and neurodegenerative disease development." (PMID 37891935, 2023). "Thus, understanding the impact of apoE isoforms on microglial response and functions, in the context of neuronal injury such as demyelination, may facilitate the development of therapeutic strategies for the treatment of neurodegenerative diseases." (PMID 36419137, 2022). "A recent preprint suggests that SARS-CoV-2 induces amyloid aggregation of several proteins involved in neurodegenerative diseases such as APLP1, ApoE, clusterin, α2-macroglobulin, PGK-1, ceruloplasmin, nucleolin, 14–3-3, transthyretin, and vitronectin." (PMID 36362302, 2022). "We review the genetic influence of two important disease-associated loci, 17q21.31 (the “MAPT locus”) and APOE, to neurodegenerative disease risk in non-European populations, touching on global population differences and evolutionary genetics by ancestry that may underlie some of these differences." (PMID 36337698, 2022). "Our findings provide critical mechanistic insights into how apoE isoforms differentially regulate microglial function and the maintenance of myelin dynamics, which may inform novel therapeutic avenues for targeting microglial dysfunctions in neurodegenerative diseases." (PMID 36419137, 2022).